CD4 (CD4 molecule)
Diseases named in the same sentence as CD4 in open-access papers (continued):
Sharing a sentence is not in itself a finding about the gene and the disease.
breast cancer (continued). "One showed that CD8+ and CD20+ lymphocytes declined in metastases, in TN breast cancer even CD4+ and CD3+ lymphocytes declined." (PMID 36627701, 2023). "In the present study, we show that breast cancer survivors (56 ± 6 years) exhibited higher levels of CD4+ central memory T cells and lower levels of CD8+ Naïve T cells compared to healthy women (45 ± 11 years)." (PMID 37324393, 2023). "CD4 + T cell density has been reported to be a unbeneficial prognostic factor in other types of cancers, e.g. lung, renal, prostate and breast cancer." (PMID 37277702, 2023). "Breast cancer patients exhibited similar counts of CD4+ CM cells to survivors (although there was large variation between individuals) and similar counts of CD8+ NA T cells to both healthy women and survivors." (PMID 37324393, 2023). "Currently, research on the relationship between CD4+Th cells and breast cancer is primarily focused on local immune responses in the tumor microenvironment." (PMID 36925914, 2023). "The percentage of Memory CD4+ T cells in the unaffected lymph nodes of breast cancer patients was increased, which inhibited tumor progression by hindering lymph node metastasis." (PMID 36983615, 2023). "As for cancerous diseases, aconite can also stimulate tumor immunity in patients with breast cancer undergoing chemotherapy, which is mediated by the upregulation of CD4+/CD8+ T cells and NK cells." (PMID 36756040, 2023). "SERD-induced inhibition of MDSCs and concurrent actions on CD8+ and CD4+ T-cells promote the interaction of immune checkpoint inhibitors with breast cancer cells and augment the curative effect." (PMID 37251404, 2023). "Studies show that increased infiltration of CD4 T cells is often predictive of a better survival outcome and favorable prognosis of breast cancer patients." (PMID 38186570, 2023). "The current study found that the activity of CD3 + and CD4 + cells decreased significantly in patients with breast cancer treated with post-operative chemotherapy, while the activity of CD8 + cells increased." (PMID 37542585, 2023). "Lastly, in a syngeneic mouse model of breast cancer, TNFSF10-deficiency in breast tumors decreased tumor-infiltrated CD4+ and CD8+ T cell quantities." (PMID 35930348, 2023). "For example, the checkpoint gene PD-L1 is regulated by NR4A1 in breast cancer cells and treatment with CDIM/NR4A1 antagonists decreased PD-L1 and enhanced immune surveillance (increased CD8 + /CD4 + ratios) in syngeneic mouse breast cancer model." (PMID 37847301, 2023). "The high CCL11 level was shown to increase the proportion of immunosuppressive CD4+CD25+Foxp3+ Tregs in a breast cancer model, indicating the pro-tumoral effect of the IL-4/CCL11 interaction." (PMID 37445941, 2023). "This study found that the proportion of CD4+Tn cells was decreased in patients with breast cancer, while the absolute number and proportion of CD4+CD57+T and CD4+ PD-1+T cells were significantly increased compared with those in patients with benign tumors." (PMID 36925914, 2023). "When CCL18 varied in arm-level gain, the infiltration levels of B cells, CD8 + cells, CD4 + T cells, macrophages and neutrophils decreased significantly in breast cancer samples." (PMID 36805828, 2023). "Other reports, however, depicted that CD4+ regulatory T cells seemed to be capable of inhibiting invasive breast cancer development from preinvasive breast cancer by suppressing protumorigenic T helper 2 cell responses." (PMID 37835488, 2023). "According to a retrospective study on breast cancer, CD4+ T cells were positively related to tumor stage, size, and metastasis and negatively related to survival." (PMID 36936412, 2023). "An important finding from this study is that compared to healthy women, breast cancer survivors within 2 years of treatment, exhibited a greater proportion of HLA-DR+ activated CD4+ and CD8+ effector memory cells." (PMID 37324393, 2023).
breast cancer (continued). "Highly expressed HSP90AB1 and HSP90B1 negatively correlated with the infiltration of CD4+ T cells in a study exploring immune infiltration in breast cancer." (PMID 38259468, 2023). "In a murine model of breast cancer cells, Shiao and colleagues reported on how polarized Th2 macrophages and CD4+ T cells mediate tumor growth after radiation therapy, in part via suppression of CD8+ T cells." (PMID 37347290, 2023). "The high TLR3 expression breast cancer tissues had a high fraction of resting CD4 memory resting T cells (p < 0.001), resting Mast cells (p < 0.001), and M1 Macrophages (p < 0001)." (PMID 37005579, 2023). "In summary, we showed that eight-weeks of exercise training decreased the counts and activation levels of CD4+ EMRA T cells among breast cancer survivors." (PMID 37252426, 2023). "4T1 bilateral breast cancer mice depleted of DCs, CD4+, or CD8+ T cells were treated with FKPN and laser irradiation." (PMID 37031242, 2023). "Uniquely, this study also shows that fat mass index is positively associated with the activation levels of CD4+ and CD8+ effector memory T cells across healthy women and breast cancer survivors." (PMID 37324393, 2023). "In breast cancer (where high levels of CXCL13 expression are an independent prognostic factor) CD4+ T cells are the dominant intratumoral source of CXCL13 and correlate with increased B cell infiltration and maturation." (PMID 37520560, 2023). "IL-6-induced p-STAT1 and p-STAT3 were lower in naïve CD4+ T cells from breast cancer patients compared to healthy donors." (PMID 37741983, 2023). "When CCL18 varied in arm-level gain, the infiltration of B cells, CD8 + cells, CD4 + T cells, macrophages and neutrophils decreased significantly in breast cancer samples." (PMID 36805828, 2023). "Among breast cancer patients, the proportion of activated CD4+ and CD8+ T cells and subsets was slightly lower than survivors and closer to the values for healthy women, but there was large inter-individual variation." (PMID 37324393, 2023). "Breast cancer patients tended to exhibit lower CD4+ TSCM counts than both groups (CD4+ TSCMs: 1.52 ± 0.70 cells/μL) but CD8+ TSCMs tended to be higher among patients compared to survivors (CD8+ TSCMs: 0.49 ± 0.18 cells/μL) but similar to healthy women." (PMID 37324393, 2023). "CD4+ T cells have been reported to increase in the tissue of lymphedema in a mouse lymph node-dissection model and in human lymphedema tissue after breast cancer surgery." (PMID 37940849, 2023). "The CD8 T cells are the predominant tumor-infiltrating leukocytes in breast cancer, followed by macrophages, regulatory T cells, CD4 T cells, etc., and the T cell subsets are involved in immune surveillance." (PMID 38186570, 2023). "In our study, we found that the proportion and absolute number of CD4+PD-1+T cells in patients with breast cancer were higher than those in patients with benign tumors, and the proportion of CD4+PD-1+T was related to clinicopathology." (PMID 36925914, 2023). "This increased proportion of CD4+ T cells recovered from tumours was consistent with the results observed in the MDA-MB-231 breast cancer model." (PMID 37684239, 2023). "Earlier studies have shown that CD4 T cells promote pulmonary metastasis in mammary carcinomas by augmenting the protumor characteristics of macrophages." (PMID 37790630, 2023). "Such differential effects have been previously reported, with Δ9-THC eliciting the proliferation of neural progenitors and of human breast carcinoma cell lines but suppressing the proliferation of activated CD4+ T cells and of non-small cell lung cancer cells." (PMID 38150302, 2023). "Breast cancer patients with seroma formation after simple mastectomy showed a CD4+ T helper cell increase in the seroma fluid samples." (PMID 35563236, 2022).
breast cancer (continued). "TIMER data was used to study the correlations between SNAI expression levels and the infiltration of six types of immune cells (i.e., B cells, CD8+ T cells, CD4+ T cells, macrophages, neutrophils, and dendritic cells) in breast cancer." (PMID 35898399, 2022). "Our findings collectively indicate robust trials of the immune system to mount sufficient tumor-specific immune response, possibly by inducing CD4+ migration and accumulation in breast cancer tissue." (PMID 35051220, 2022). "This is similar to a published study of breast cancer, they reported that paclitaxel impairs the expansion of immune cells, including CD4+ T cells." (PMID 36474268, 2022). "In breast cancer patients, Her2/neu helper peptides administered as peptide-pulsed type 1 DC vaccine induced durable specific CD4+ T cell responses and complete regressions." (PMID 35008422, 2022). "Further, the expression of RUNX2 was associated with the infiltration of CD4 +T cells, neutrophils, B cells, CD8 + T cells, macrophages, and dendritic cells in breast cancer." (PMID 36092942, 2022). "MWA for breast cancer in 35 patients resulted in 32 patients having complete ablation of the tumor, with an increase in immune CD4+ T cell and IFN-γ compared to surgically resected tumors (n = 13)." (PMID 36612192, 2022). "Our findings demonstrate that TSLP-stimulated CD4+ T cell immunity can block breast cancer growth by inducing a cellular senescent phenotype in advanced breast tumors." (PMID 36467403, 2022). "We found that classical Th1 cytokines, interferon-gamma (IFN-γ) and tumor necrosis factor-alpha (TNF-α), mediated the antitumor effect of TSLP-activated CD4+ T cells against advanced breast cancer through the induction of cellular senescence." (PMID 36467403, 2022). "Our findings reveal a novel mechanism of TSLP-activated CD4+ T cell immunity against advanced breast cancer, mediated by cellular senescence as a distinct effector mechanism for cancer immunotherapy." (PMID 36467403, 2022). "IRS1 is closely related to the immune microenvironment and can affect CD4+ T cells and IFN-γ levels, and IRS1 was associated with resistance to multiple chemotherapeutic agents in breast cancer cells." (PMID 35387129, 2022). "The infiltration of CD8+ and CD4+ T cells was also decreased in the DM complicated with breast cancer group." (PMID 35578660, 2022). "In a model of breast cancer, elevated MIF expression supported tumor growth while a loss of MIF promoted the anti-tumor immune infiltration of CD4+/CD8+ T cells producing IFNγ, which supported the MIF immunosuppressive function." (PMID 36496973, 2022). "More clinically relevant, LAIT upregulated genes in CD8+ T and CD4+ T cells that positively correlated with extended survival of breast cancer patients." (PMID 35808806, 2022). "As shown, decreased B cells and CD4+ memory T cell infiltration or increased macrophage and basophil infiltration associated with high COL11A1 expression suggest poor prognosis in breast cancer patients." (PMID 36160004, 2022). "TSLP, as an epithelium-derived alarmin, induces a robust and tumor-specific CD4+ T cell immunity against breast cancer." (PMID 35657353, 2022). "Instead of cytotoxicity, CD4+ Th2 cells directly block breast carcinogenesis by inducing the terminal differentiation of breast cancer cells." (PMID 35657353, 2022). "Breast cancer tumors with high amounts of T-regs (CD4+ FOXP3) have a poor prognosis as the T-regs exhaust the local T cell immune response." (PMID 35804950, 2022). "The remarkably impaired absolute counts of the CD3+, CD4+, CD8+, B, and NK cells in patients with breast cancer can be used as potential susceptible biomarkers to evaluate the patient's immune status." (PMID 36051923, 2022). "Lower levels of peripheral and breast cancer tissue CD39+CD4+ T lymphocyte were detected in G3 TNBC compared with G2." (PMID 35051220, 2022).
breast cancer (continued). "Studies have shown that the abundance of naïve CD4+ T cells is closely related to Tregs, which indicates that breast cancer patients have a poor prognosis." (PMID 36032097, 2022). "The CXCL13-producing CD4+ T cells reported in breast cancer and nasopharyngeal cancer had similar characteristics." (PMID 35552285, 2022). "The tumor site had a higher percentage of CD4+CD25+CD127-FOXP3+ Tregs than the peripheral circulation of breast cancer patients and age-/sex-matched healthy donors." (PMID 35222362, 2022). "Here, we provide evidence that high expression of NR1H3 is strongly correlated with multiple immune infiltration in breast cancer tissues, including B Cells, CD4+ T Cells, CD8+ T Cells, neutrophils, macrophages and DCs." (PMID 36699456, 2022). "By contrast, the peripheral blood of breast cancer patients exhibits reduced numbers of lymphocytes and proportions of CD4+T cells and CD19+ B cells following standard RT or intraoperative RT." (PMID 36139665, 2022). "CPT acts like IL-12 and causes the release of perforin from CD4+ T cells through the phosphorylation of the JAK2/STAT4 pathway, mainly inhibited the growth of breast cancer cells." (PMID 36188552, 2022). "In breast cancer patients, tumor-infiltrating CD4+ lymphocytes were shown to be a vital source of CXCL13." (PMID 35844446, 2022). "In contrast, CD45posCD3posCD8pos cytotoxic T cells disclosed an opposite trend: the CD4/CD8 ratio is significantly unbalanced in the direction of breast cancer patients." (PMID 36010863, 2022). "In patients with breast cancer, the frequency of Tsen CD4+ T cells was also significantly increased." (PMID 35875098, 2022). "The abundance of naive CD4+ T cells and Tregs is closely correlated, and both indicate poor prognosis for breast cancer patients." (PMID 34793335, 2022). "Further, MMTV-RONΔMyeloid mammary tumors compared with controls show increased numbers of CD8a+ T cells and CD4+ T cells." (PMID 35626096, 2022). "CCL5 affects the Treg/CD4+CCR5+ cell ratio in breast cancer patients through CCR5, thus affecting breast cancer metastasis and prognosis." (PMID 36033472, 2022). "More importantly, LAIT‐specific upregulated genes in CD8+ and CD4+ T cells positively correlated with extended breast cancer patient survival by GSVA analysis of TCGA data." (PMID 35808806, 2022). "Based on our recent observations using breast cancer model and CD4 depletion studies, CD4 T-cell activation (which results from LAMP1-antigen fusion) was found to be essential for the initial stages of CD8 T-cell activation." (PMID 35651802, 2022). "The results showed that high expression of TMPRSS2 in breast cancer has a poor prognosis in enriched CD4+ T cells (HR = 1.78 p < 0.01) and enriched CD8+ T cells (HR = 3.52 p < 0.001)." (PMID 35558557, 2022). "In breast cancer, the presence of tumor-infiltrating lymphocytes with a high CD4+/CD8+ ratio is an indicator of poor prognosis." (PMID 35765486, 2022). "In the 4T1 breast cancer model, a higher frequency of CD4+ and CD8+ T cells producing IFNγ, TNFα, or IL-2 was found in mice treated with T. usneoides." (PMID 36358804, 2022). "Further, we adopted TIMER to examine the relationship of CRIM1 with invading immune cells in breast cancer, consisting of CD4+ T-cells, neutrophils, CD8+ T-cells, macrophage M1, B-cells, NK, endothelial cells, and Tregs." (PMID 35600360, 2022). "The overall impact of anti-HER2 induced radiosensitization on the greater immune system should be further studied in a humanized model of HER2+ breast cancer and probing of CD4+ and CD8+ T-cell trafficking." (PMID 35205763, 2022). "The breast cancer suppression in the Tslptg TslprKO + WT CD4+ T cell group was more pronounced when the tumor cells expressed OVA antigen (PyMtOvatg TslprKO, P < 0.0001)." (PMID 35657353, 2022).
breast cancer (continued). "Consistent with previous results, CD8+ subsets and Tregs were associated with improved survival in breast cancer patients, and a significant correlation between CD4+ naive T cell expression and OS was identified in breast cancer subtypes HER2-positive and TN." (PMID 36551522, 2022). "Jóźwicki reported that breast cancer patients with reduced CD4+ T cell infiltration had shorter overall survival, and CD4+ T cells are a critical prognostic indicator, consistent with our findings." (PMID 35814472, 2022). "Using an established MMTV-PyMttg breast cancer cell line, we demonstrate that TSLP-stimulated CD4+ T cells possess an antitumor effect in advanced breast cancer." (PMID 36467403, 2022). "For example, similar CD4+ T-cell populations exist in different breast cancer patients, such as homogenous population of Treg immunosuppressive cells prevalently present in all breast cancer subtypes." (PMID 35514975, 2022). "The infiltration of CD8+, CD4+, and mucosal-associated invariant T-cell (MAIT) cells was also significantly decreased in the breast cancer complicated with DM group." (PMID 35578660, 2022). "It has been found that CD4 + T cells infiltrating breast tumor tissue can effectively predict the survival of breast cancer and can examine patients through their signatures." (PMID 36618928, 2022). "Before bone metastasis of breast cancer, tumor cells induce CD4+ T cells to express pro-osteoclastogenic cytokines IL-17F and RANKL (Receptor Activator of Nuclear Factor-κB Ligand) and promote the occurrence of bone loss." (PMID 36611857, 2022). "CXCR4 receptor not only exists on the surface of CD4+ T cells but also highly expressed on the surface of breast cancer cells." (PMID 35979048, 2022). "We show that in CD4+ T-cells from most of the investigated breast cancer patients a number of these STPs are overactive." (PMID 35158758, 2022). "Previous studies have reported that low-levels of tumor infiltration in tumor tissues resulted in worse outcomes of cancer patients, including in CD4+ T cells and for macrophages in gastric cancer, as well as for B cells in breast cancer." (PMID 35892344, 2022). "Pharmacodynamic experiments confirmed that the anti-PD-L1 antibody can strongly inhibit primary breast cancer and increase levels of CD4+ and CD8+ T cell at the tumor site." (PMID 36303207, 2022). "Collectively, these findings demonstrate that Th2 polarization is essential for TSLP-induced CD4+ T cell immunity against breast cancer development." (PMID 35657353, 2022). "Underlining the functional heterogeneity of CAFs, they report a similar mechanism in breast cancer where PDPN+ CAFs significantly inhibited the proliferation of CD4+ and CD8+ T cells in co-culture via production of NO while PDPN- CAFs do not." (PMID 35479076, 2022). "The frequency of CD4+ T lymphocytes in breast cancer tissue was higher than in the periphery and higher than in healthy tissue." (PMID 35051220, 2022). "Taken together, we provide predictive evidence that LAIT has a greater potential to prolong patient survival by driving CD8+ and CD4+ T cell activation and favourable gene signatures that correlate with greater overall survival of breast cancer patients." (PMID 35808806, 2022). "TGF-β blockade leads to CD4+ Th2 cell-induced cancer cell hypoxia through the remodeling of the tissue vasculature in an MMTV-PyMt murine breast cancer model." (PMID 35565302, 2022). "On the other hand, a study investigated the distribution of IL-17-producing CD4+ T-cells in relation to Treg cells in tumor-infiltrating lymphocytes (TILs) and peripheral blood mononuclear cells (PBMCs) collected from breast cancer patients." (PMID 35954312, 2022). "To investigate the role of adaptive immune cells in TSLP-induced breast cancer suppression, we transferred naive CD4+ or CD8+ T cells from WT mice into MMTV-PyMTtg, Rag1−/− (PyMttg Rag1KO) animals with or without K14-Tslp transgene." (PMID 35657353, 2022).